BRIP1 (BRCA1 interacting DNA helicase 1)
Diseases named in the same sentence as BRIP1 in open-access papers (continued):
Sharing a sentence is not in itself a finding about the gene and the disease.
breast cancer (continued). "Additionally, variants of unknown/uncertain significance (VUS) in breast cancer susceptibility genes CHEK2, BRCA2 and BRIP1 were determined to be present in three different PABC patients (15%)." (PMID 34011307, 2021). "In addition, the UGM can be used to screen many breast cancer-associated genes, such as BRCA1, BRCA2, PTEN, BRIP1, etc., provides better accuracy, robustness and efficiency, the method of identification differentially expressed genes in high-throughput sequencing." (PMID 31865918, 2019). "The human BRIP1 gene (also named FANCJ or BACH1) is located on chromosome 17q22, comprising of 19 introns and 20 exons, and encodes BRCA1-associated C-terminal helicase 1 And its mutations that affect helicase activity have been identified in patients suffering early-stage breast cancer." (PMID 29466248, 2018). "Mutations in BRIP1/FANCJ are associated with breast cancer, but, so far, not with osteosarcoma." (PMID 29507082, 2018). "Several FA genes (FANCD1/BRCA2, FANCN/PALB2, FANCJ/BRIP1, FANCO/RAD51C, and FANCS/BRCA1) are high- or moderate-risk breast or ovarian cancer susceptibility genes and previous studies have connected also heterozygous FANCM mutations with breast cancer predisposition." (PMID 28702895, 2017). "However,other genes, such as ATM, PALB2, BRIP1, CHEK, BARD1, while lower in frequency, may also increase breast cancer risk." (PMID 29093764, 2017). "Intriguingly, no BRIP1-mutated FA family had a family history of breast cancer." (PMID 27716388, 2016). "However, the phenotypic effects of BRIP1 dysfunction and its role in breast cancer tumorigenesis remain unclear." (PMID 24040146, 2013). "The BRIP1 gene (BRCA1 interacting protein-1) encodes a protein that is a DNA/RNA helicase of the REC Q family that binds to the carboxy-terminus of BRCA1 protein conferring an activity involved in DNA repair and variants of this gene can predispose to breast cancers." (PMID 20111735, 2010). "However, it is still possible that BCoR-L1 could be involved in breast cancer predisposition as a moderate- or low-penetrance risk gene, as has been found with CHEK2, BRIP1, and PALB2 in large studies of BRCAX cases and controls." (PMID 17697391, 2007). "BACH1 (BRCA1-associated C-terminal helicase 1, also known as BRCA1-interacting protein 1, BRIP1; GenBank: NM_032043) belongs to a DEAH helicase family and interacts in vivo with BRCA1, the protein product of one of the two major genes for hereditary breast cancer susceptibility." (PMID 16430786, 2006). "For example, for breast cancer, international guidelines now classify genes as high (BRCA1/2), moderate (BARD1), and low penetrance (BRIP1) and favor mastectomy for high penetrance but surveillance with magnetic resonance imaging and mammograms for others." (PMID 40282361, 2025). "BOADICEA V5’s newest version includes the effects of pathogenic variants (PVs), not restricted to BRCA1 and BRCA2 genes but also in PALB2, CHEK2, ATM, and BARD1 for the breast cancer model and RAD51D, RAD51C, and BRIP1 for the ovarian cancer model." (PMID 39590369, 2024). "Nonetheless, other genes in the HRR pathway, such as the RAD51c, PALB2, BRIP1, and BARD1 gene defects, have also been shown to impact breast cancer progression and outcomes." (PMID 38397152, 2024). "Family history of breast cancer was observed either in first-, second- or third-degree relatives in all patients except in the patients carrying a VUS in the APC, BRIP1 and NF2 genes." (PMID 37277882, 2023). "Prognostic analysis showed that BRIP1 expression (OS, p = 0.006l; PFS, p = 0.036) was related to an improved prognosis for HER2+ breast cancer patients." (PMID 35707004, 2022).
breast cancer (continued). "To confirm these data, we assessed by RT-qPCR the expression of both BRIP1 and ALDH2 in 9 breast cancer cell lines representing different breast tumor subgroups." (PMID 34454516, 2021). "Furthermore, mutations in moderate-penetrance genes such as BRCA1 interacting protein C-terminal helicase 1 (BRIP1), ataxia telangiectasia mutated (ATM), partner and localizer of BRCA2 (PALB2), and checkpoint kinase 2 (CHEK2) are associated with a two-fold increased risk of developing breast cancer." (PMID 33027908, 2020). "It is now apparent that mutations of several other genes, such as BARD1, PALB2 (Partner And Localizer Of BRCA2) and BRIP1 (BRCA1 Interacting Protein C-Terminal Helicase 1), contribute to familial breast cancer." (PMID 29292755, 2017). "Many of the known hereditary breast cancer genes such as BRCA1, BRCA2, CHEK2, ATM, and FANCJ/BRIP1 work together in a DNA repair pathway, raising the possibility that other genes in this pathway also predispose to breast cancer." (PMID 18053174, 2007). "It appears unlikely, therefore, that FANCD2, BRIP1/BACH, LMO4 and SFN account for more than a small proportion of inherited forms of breast cancer." (PMID 16280053, 2005). "HRD extends beyond BRCA1/BRCA2 mutations to include non-BRCA genes (RAD51C/RAD51D, BRIP1, BARD1, ATM, PALB2), broadening actionable targets across ovarian and breast cancer subtypes, including HER2-positive (30–40%) and luminal subtypes (15–25%)." (PMID 40864792, 2025). "After exploring the differential expression patterns of BRIP1 between tumors and normal tissues, we also used the HPA dataset to examine the protein expression patterns of BRIP1 in breast cancer, lung cancer, colorectal cancer, liver cancer, and prostate cancer." (PMID 36907870, 2023). "Moreover, next-generation sequencing revealed that beyond BRCA1/2, mutations in homologous recombination effectors, such as PALB2, RAD51, ATM, BRIP1, BARD1, and CHEK2 also occur in breast cancer." (PMID 36613148, 2023). "Our study did not support RAD50, BRIP1 and RAD51C as breast cancer susceptibility genes in the Chinese population, consistent with results from case-control studies in Caucasian women." (PMID 34606182, 2021). "Mutations in PALB2/FANCN increase breast and pancreatic cancer incidence, while truncating variants of BRIP1/FANCJ and RAD51C/FANCO increase ovarian but not breast cancer." (PMID 32962238, 2020). "COL8A1 proved downregulated in both BRIP1-knockdown breast cancer cells and MCF10A CDH1-/- non-cancer breast cells." (PMID 32818022, 2020). "Mutations in the BRIP1 gene (BRCA1 Interacting Protein C- terminal helicase 1) are known to increase the risk of ovarian and breast cancers, but this genes association with colon cancer has not been previously reported." (PMID 31064327, 2019). "Mutation analysis of the BRCA1-interacting genes FANCD2, BRIP1/BACH, LMO4 and SFN in a large number of non-BRCA1/2 breast cancer families did not identify any highly penetrant, pathogenic mutations." (PMID 16280053, 2005). "In addition, the last V5 version of BOADICEA incorporates the effects of pathogenic variants (PVs), not only in BRCA1 and BRCA2 genes, but also in PALB2, CHEK2, ATM and BARD1 for the breast cancer model and RAD51D, RAD51C and BRIP1 for the ovarian cancer model." (PMID 35886069, 2022). "Indeed, it has been reported that the BRIP1 and RAD51 pathogenic variants confer at least a 6-fold increased risk for OC, but not for breast cancer, in contrast to the NBN and CHEK2 genes." (PMID 30441849, 2018). "Additional genes tested with a definite link to breast cancer included CDH1 (n=29) and BARD1 (n=19) testing negative in addition to 72 samples testing negative for BRIP1." (PMID 38609177, 2024).
ovarian carcinoma (165 papers, 2005 to 2026). A malignant neoplasm originating from the surface ovarian epithelium. "While biallelic loss of function causes Fanconi anemia, heterozygous carriers of pathogenic BRIP1 variants have been shown to face an increased susceptibility to ovarian cancer, with lifetime risks by age 80 estimated at approximately 4–9%." (PMID 41528496, 2026). "BRIP1 is the third most frequently linked gene to ovarian cancer susceptibility, with pathogenic variants detected in 0.9 – 2.5% of ovarian cancer patients." (PMID 40800071, 2025). "BRIP1 mutations increase the risk of ovarian cancer, and it has been demonstrated that BRIP1-deficient cells are sensitive to combined treatment with platinum drugs and PARPi." (PMID 41465280, 2025). "We identified no studies specifically focusing on the benefit of PARP-inhibitors in BRIP1-mutated ovarian cancer." (PMID 40988318, 2025). "This study revealed a high prevalence of a BRIP1 splice site pathogenic variant (c.1936 + 1G > A) among Somali women with ovarian cancer, with 60 % of those tested (3 out of 5) carrying this pathogenic variant." (PMID 39554377, 2024). "Both the literature data and the results presented in this article indicate that FANCI and BRIP-1 proteins are associated with ovarian cancer." (PMID 39767562, 2024). "As shown in the literature, mainly polymorphisms of FANCI and BRIP-1 genes and their association with ovarian cancer have been studied." (PMID 39767562, 2024). "BRIP1 has been observed as the third-most commonly associated gene with ovarian cancer susceptibility, with nearly 0.9% to 2.5% of all ovarian cancer patients carrying a variant." (PMID 38397209, 2024). "Pathogenic variants in FANCJ/BRIP1 are associated with Fanconi anemia (FA), a rare hereditary chromosome instability disorder, and are also implicated in hereditary breast and ovarian cancer." (PMID 39011897, 2024). "BRIP-1 has so far been studied for mutations in this gene and their association with ovarian cancer." (PMID 39767562, 2024). "The association of ovarian cancer with BRIP1 variants was RR = 3.94, 95% CI = 2.44 to 6.22, p = 1 × 10−8)." (PMID 39767562, 2024). "BRIP1 is instead included on the corresponding gene panel for ovarian cancer predisposition, together with BRCA1, BRCA2, PALB2, RAD51C, RAD51D and the Lynch syndrome genes." (PMID 37563628, 2023). "In ovarian cancer, a deleterious mutation of BRIP1 was associated with low-grade histology and led to an increased risk of the disease." (PMID 37153833, 2023). "All four germline BRIP1 pathogenic variants were detected in women aged <70 at diagnosis with at least one first- or second-degree relative diagnosed with breast or ovarian cancer." (PMID 36765687, 2023). "Other genes implicated in ovarian cancer, BRIP1, RAD51D, PALB2, and RAD51C, had a yield of 1.1% (n = 12), 0.8% (n = 9), 0.3% (n = 3), and 0.09% (n = 1), respectively." (PMID 35971132, 2022). "BRCA1 and BRCA2 were shown to be susceptibility genes for ovarian cancer, and the BRIP1, RAD51C, rad51D and mismatch repair genes also play a role in this disease." (PMID 35910206, 2022). "BRIP1 is a homologous recombination-related gene, and previous reports included BRIP1 as a risk gene for ovarian cancer." (PMID 36324591, 2022). "BRIP1 gene is reported to moderately increase the risk of breast and/or ovarian cancer, (OMIM: #605882) though its association with colorectal cancer is sparsely reported in the literature and exact risks are not known." (PMID 34326862, 2021). "In recent years, it has been recognized that deleterious germline variants of BRIP1 are highly susceptible to ovarian cancer." (PMID 35008774, 2021).
ovarian carcinoma (continued). "More recently, additional genes associated with increased ovarian cancer risk have been identified, including BRIP1, RAD51C, and RAD51D." (PMID 33926482, 2021). "In order to better characterize the clinical presentation of women with a PV in a moderate penetrance ovarian cancer-risk gene, we evaluated women with a PV in BRIP1, RAD51C, or RAD51D identified during hereditary cancer genetic testing." (PMID 33926482, 2021). "The implication of pathogenic BRIP1 variants in ovarian cancer predisposition have been described before." (PMID 32756499, 2020). "The association between protein truncating variants in BRIP1 and risk of ovarian cancer has been confirmed in other analyses (associated risks ranged from 2.6 to 6.4)." (PMID 33086730, 2020). "Three studies have reported the frequency of protein truncating variants in BRIP1 by ovarian cancer histotype." (PMID 33086730, 2020). "Pathogenic germline variants in BRIP1 are the most common mutation found in ovarian cancer after BRCA1/2 with a frequency of approximately 1% of the EOC cases." (PMID 33086730, 2020). "Additional studies are needed to further assess the contribution of germline protein truncating variants in BRIP1 in the ovarian cancer histotypes." (PMID 33086730, 2020). "For example, a recent study established that rare missense alleles of BRIP1/FANCJ confer risk for breast as well as ovarian cancer." (PMID 32120966, 2020). "BRIP1 and variant rs4986765 are related to familial cancer of the breast, neoplasms of the ovary, hereditary cancer-predisposing syndrome, and Fanconi anemia, which is also associated with the variant rs4713867 (FANCE) gene." (PMID 32708070, 2020). "Further interactors in this pathway, in particular BRIP1/FANCJ, mainly have been linked to ovarian cancer risk." (PMID 31467304, 2019). "BRIP1 frameshift mutation, c.2040_2041insTT, is estimated to increase the risk of ovarian cancer by 8.1-fold." (PMID 31366178, 2019). "The deleterious mutation of BRIP1 (BRCA1-interacting protein C-terminal helicase 1), which aids unwinding DNA for repair, is associated with increased risk of ovarian cancer, in particular HGSC tumor phenotype." (PMID 31366178, 2019). "Monoallelic mutations in five FA genes (BRCA1, BRCA2, PALB2, RAD51C, BRIP1) have now been confirmed to predispose to breast or ovarian cancer while biallelic mutations in these genes cause FA3." (PMID 31467304, 2019). "Studies suggest that the germline BRIP1 mutations can be considered as a moderate risk for ovarian cancer, and prophylactic surgery is taken into consideration for patients carrying BRIP1 mutation." (PMID 30975222, 2019). "Numerous previous studies have suggested that BRIP1 polymorphisms were potentially related to susceptibility of human cancers, especially breast, cervical, and ovarian cancer." (PMID 29466248, 2018). "BRIP1 germline mutations have recently been shown to be associated with an increased risk in epithelial ovarian cancer and some high grade ovarian serous disease." (PMID 29755699, 2018). "A truncating BRIP1 mutation has been identified in a small proportion of women suffering from epithelial ovarian cancer in Iceland." (PMID 29755699, 2018). "The BRIP1 rs2048718, rs4986764, and rs4968451 SNPs, all evaluated in our study, have been associated with susceptibility to meningioma, breast, and ovarian cancer." (PMID 28415781, 2017). "BRIP1, also known as BACH1 or FANCJ, is an essential tumor suppressor gene based on the identification of clinically relevant BRIP1 mutations in several cancers like hereditary breast and ovarian cancers and childhood cancer syndrome." (PMID 28968953, 2017).
ovarian carcinoma (continued). "Germline mutations in at least four Fanconi Anemia genes (BRCA2, PALB2, RAD51C, BRIP1) have thus far been found to contribute to the inherited risk of breast or ovarian cancer." (PMID 24465539, 2014). "For example, whole genome-sequencing of Icelanders led researchers to discover frameshift mutations in the BRIP1 (FANCJ) gene that vastly elevate the risk of invasive ovarian cancer." (PMID 25374583, 2014). "For example, BRIP1 encodes Fanconi anemia group J protein, which appears to be important in ovarian cancer where it potentially act as an antioncogene." (PMID 24205334, 2013). "The BRIP1 protein, also known as FANCJ or BACH1, acts as a BRCA1- associated helicase, and mutations of BRIP1 also predispose to ovarian cancer with apparently higher penetrance." (PMID 24025454, 2013). "Taken together, these data suggest that BRIP1 is a good candidate for moderate/low penetrance genetic susceptibility to breast and ovarian cancer." (PMID 17342202, 2007). "In conclusion, we have genotyped 12 tSNPs that tag the common variants in BRIP1 in breast and ovarian cancer case control series." (PMID 17342202, 2007). "The functional interaction between the DNA helicase BRIP1 and the breast/ovarian cancer susceptibility gene BRCA1 makes common variants in BRIP1 good candidates for low to moderate penetrance susceptibility to both breast and ovarian cancer." (PMID 17342202, 2007). "BRIP1, detected in two patients, has also been linked to an increased ovarian cancer risk." (PMID 40926019, 2026). "Notably, individuals from two families carrying germline variants in BRCA and BRIP1 exhibited a spectrum of malignancies, including esophageal cancer, renal cancer, ovarian cancer, laryngeal cancer, and lung cancer." (PMID 40777133, 2025). "FANCJ/BRIP1 is frequently mutated in breast and ovarian cancers, as well as in other tumour types." (PMID 39927196, 2025). "Furthermore, because BRIP1 also confers a risk of ovarian cancer, exploring the relative significance of a BRIP1 mutation in males vs females would be interesting." (PMID 38912178, 2024). "Previously, a meta-analysis based on 29400 patients with 116000 controls from 63 studies found BRIP1 was associated with a high risk of ovarian cancer and the HRR pathway might be involved." (PMID 37153833, 2023). "Pathogenic germline variants in BRIP1 confer a high risk for ovarian cancer." (PMID 36550207, 2023). "Besides BRCA1/2, the implication in CRC occurrence of FANCJ/BRIP1 mutations, a moderate-risk factor for ovarian cancer, has attracted considerable attention." (PMID 35330396, 2022). "Women with mutations in moderate penetrance genes, such as RAD51C, RAD51D, and BRIP1 mutations, have a lifetime risk of 5.2–12% and may benefit from ovarian cancer screening." (PMID 32098383, 2020). "To more precisely estimate the ovarian cancer risk attributed to BRIP1, RAD51C, and RAD51D mutations, we performed a meta-analysis based on a comparison of a total of ~ 29,400 ovarian cancer patients from 63 studies and a total of ~ 116,000 controls from the gnomAD database." (PMID 32359370, 2020). "However, a recent study reported that, although the germline mutation of BRIP1 is a strong risk factor in ovarian cancer, it is difficult to view it as a significant factor in BC44,45." (PMID 32719318, 2020). "Pathogenic variants in BRIP1 have been associated with increased risk of OC34–36, but it remains to be investigated whether the germline variant in BRIP1 is the cause for the ovarian cancers in both sisters." (PMID 31882575, 2019). "Another frameshift mutation in BRIP1, c.1702_1703del, may also contribute to increased risk of ovarian cancer, although a larger sample size is needed." (PMID 31366178, 2019). "BRIP1 germline mutations are also associated with an increased risk of ovarian cancer." (PMID 30975222, 2019).